RPRD2 (regulation of nuclear pre-mRNA domain containing 2)
Synonyms: KIAA0460; HSPC099; FLJ32145
Tractability: PROTAC: ubiquitination databases record sites on it; its protein half-life has been measured.
Gene: Protein-coding gene on chromosome 1 (150,363,091 to 150,476,566, forward strand). Ensembl gene ENSG00000163125.
Subcellular location (Human Protein Atlas): Nucleoplasm; Vesicles
Pathways (Reactome):
Gene expression (Transcription): RNA polymerase II transcribes snRNA genes
Gene Ontology:
Molecular function: RNA polymerase II complex binding; RNA polymerase II C-terminal domain binding
Biological process: mRNA 3'-end processing
Cellular component: transcription preinitiation complex; nucleoplasm
Genetic constraint (gnomAD): Loss-of-function variants: 7 observed, 90.61 expected, observed/expected ratio (o/e) 0.0773, 90% interval 0.043 to 0.14. The upper end of that interval is the gene's LOEUF score, 0.14, which puts it in group 1 of 6, group 1 being the genes least tolerant of losing a copy. Missense variants: 1,495 observed, 1,789.2 expected, observed/expected ratio (o/e) 0.84, 90% interval 0.8 to 0.87. Synonymous variants: 680 observed, 689.73 expected, observed/expected ratio (o/e) 0.99, 90% interval 0.93 to 1.05.
Homologues: Orthologues: chimpanzee RPRD2 (99% identical), macaque RPRD2 (99% identical), pig RPRD2 (97% identical), dog RPRD2 (96% identical), rabbit RPRD2 (96% identical), guinea pig RPRD2 (92% identical), rat Rprd2 (91% identical), mouse Rprd2 (91% identical), tropical clawed frog rprd2 (57% identical), zebrafish rprd2b (28% identical), zebrafish rprd2a (27% identical), Drosophila melanogaster CG15160 (16% identical), and 1 more. Paralogues in human: RPRD1A (7% identical), RPRD1B (7% identical).
Diseases named in the same sentence as RPRD2 in open-access papers:
RPRD2 is named in the same sentence as 8 diseases in open-access papers, as found by Europe PMC text mining. Sharing a sentence is not in itself a finding about the gene and the disease. The quoted sentences say what the papers report.
breast carcinoma (1 paper, 2018). "Notably, four lncRNAs (lnc-RPRD2-3:1, lnc-KCNA5-3:4, lnc-CFP-1:1 and lnc-CD164L2-1:1) correlated strongly with the mutation status of IGF2R, a tumor suppressor commonly mutated in human liver and breast cancer." (PMID 29416609, 2018).
HIV-1 infection (1 paper, 2023). The type species of lentivirus and the etiologic agent of acquired immunodeficiency syndrome (AIDS). "Subsequently, RPRD2 (or RNA-associated early-stage antiviral factor) has been shown to be upregulated upon T cell activation, is highly expressed in myeloid cells, binds viral reverse transcripts, and potently restricts HIV-1 infection." (PMID 37882563, 2023). "Upon siRNA knockdown of RPRD2, a more than 50-fold increase in HIV-1 infection was seen, and overexpression of a GFP-RPRD2 fusion protein led to an inhibition of viral replication as measured by p24 immunostaining." (PMID 37882563, 2023). "Further elucidation of RPRD2 mechanisms will benefit our understanding of innate immune control and pathogenesis of HIV-1 infection but may also have wider implications for the regulation of cellular transcription." (PMID 37882563, 2023).
mental disorder (1 paper, 2020). A disease that has its basis in the disruption of mental process. "Interestingly, cross-lagged analyses revealed that the expression of RPRD2 (Regulation Of Nuclear Pre-MRNA Domain Containing 2) at w1 can be influenced by CBCL at w0, though very few studies have investigated this gene and none in mental disorders." (PMID 32184383, 2020).
oral cancer (1 paper, 2023). "This study permitted the proposal of 8 salivary biomarkers for oral cancer in patients previously infected with HPV (RPRD2, PSCA, MCM2, CDKN2A, BAK1, HSPA1A, TANK, MAP2K1)." (PMID 37599356, 2023).
viral infection (1 paper, 2023). "Gene ontology (GO) analysis showed that, overall, proteins interacting with RPRD2 are involved in antiviral and stress responses, and immune pathways responding to viral infections." (PMID 37882563, 2023). "This depletion of RPRD2 was observable despite a cellular response to viral infection which increased expression levels of RPRD2 in both HeLa cells and monocyte-derived macrophages." (PMID 37882563, 2023). "However, the described enrichment of function regarding innate immune genes suggests studying RPRD2-driven gene expression in the context of innate immune cells, particularly during viral infection or cell stress may be of interest for further study." (PMID 37882563, 2023).
cancer (1 paper, 2020). A tumor composed of atypical neoplastic, often pleomorphic cells that invade other tissues. "Best predicted cancer immunotherapy proteins with BC were RPS27, SUPT4H1, CLPSL2, POLR2K and RPL38, and the most altered ones were POLR2K, ASH2L, MED30, NSL1 and RPRD2." (PMID 32444848, 2020).
infection (1 paper, 2023). The state of being infected such as from the introduction of a foreign agent such as serum, vaccine, antigenic substance or organism. "Human RPRD2 was also shown to inhibit infection of HIV-2 and strains of simian immunodeficiency virus (SIV) from African green monkey, macaque, and sooty mangabey by between 15- and 126-fold, showing that RPRD2 is a generalized lentiviral restriction factor." (PMID 37882563, 2023). "Nevertheless, these results suggested that RPRD2 acts early in infection and leads either directly or indirectly to a decrease in viral reverse transcripts." (PMID 37882563, 2023).
RPRD2 also shares sentences with these, for which no sentence is quoted: tumor (1 paper).